DDAH1 (dimethylarginine dimethylaminohydrolase 1)
Diseases named in the same sentence as DDAH1 in open-access papers (continued):
Sharing a sentence is not in itself a finding about the gene and the disease.
hyperhomocysteinemia (2 papers, 2012 to 2019). A serious metabolic condition caused by mutations in the MTHFR gene, medications, or nutritional deficiency. "Ddah1 overexpression increases vascular nitric oxide levels and protects against hyperhomocysteinemia-induced alterations in cerebral arteriolar structure and vascular muscle function." (PMID 23028951, 2012).
insomnia (2 papers, 2022 to 2024). A sleep disorder characterized by difficulty in falling asleep and/or remaining asleep. "The proanthocyanidins exerted anti-insomnia effect to rats by regulating NO/ADMA/DDAH pathway, showing as increasing levels of 5-HT, GABA and NO, and protein and mRNA expressions of DDAH1, DDAH2 and nNOS, and decreasing levels of NE, Glu, ADMA and 8-isoprostane, in brain." (PMID 36267901, 2022).
liver cancer (2 papers, 2019 to 2021). An epithelial or non-epithelial malignant neoplasm that arises from the liver. "Hypoxia, which is often observed in solid tumors, induced DDAH1 expression in liver cancer HepG2 cells, however the exact mechanism underlying this induction remains to be elucidated." (PMID 31993367, 2019). "DDAH1 is important for the regulation of angiogenesis in human HCC, and its expression is increased in patients with liver cancer." (PMID 33505467, 2021).
liver diseases (2 papers, 2017 to 2022). "As a critical enzyme for ADMA degradation, DDAH1 is highly expressed in the liver and might play an important role in the pathophysiology of multiple liver diseases." (PMID 35624743, 2022).
liver dysfunction (2 papers, 2018 to 2022). "Growing evidence suggests that liver dysfunction is associated with increased plasma ADMA levels and reduced hepatic DDAH1 activity/expression." (PMID 35624743, 2022). "Impaired DDAH1 activity and lowered DDAH1 expression in the liver are likely to be the mechanisms by which liver dysfunction leads in elevated ADMA levels." (PMID 35624743, 2022). "In this study, genetic background matched Ddah1-/-, DDAH1 transgenic (DDAH1-TG), and wild-type (WT) mice were used to explore the effect of DDAH1 on APAP-induced liver dysfunction and hepatic oxidative stress." (PMID 35624743, 2022). "DDAH-1 for example is highly expressed in the kidney and liver and as FD patients do not typically show liver dysfunction enzymatic ADMA elimination might be sufficient, whereas SDMA accumulates due to the typical early occurring renal insufficiency in FD." (PMID 30159316, 2018).
liver fibrosis (2 papers, 2022 to 2025). "APAP treatment also caused more liver fibrosis in the Ddah1-/- mice than in the WT mice." (PMID 35624743, 2022).
lung fibrosis (2 papers, 2022). "As indicated by blue color area in Masson staining (deep red arrows), PM2.5 exposure caused lung fibrosis in both WT and Ddah1−/− mice." (PMID 36242005, 2022).
malaria (2 papers, 2010 to 2015). Malaria is a serious and sometimes fatal disease caused by a parasite that commonly infects a certain type of mosquito which feeds on humans. "Recently, a genome-wide association study in children found that a polymorphism in the gene encoding DDAH-1 was associated with an increased likelihood of severe malaria." (PMID 20421938, 2010). "In Gambian children, an intronic DDAH1 polymorphism is associated with susceptibility to severe malaria, raising the possibility that DDAH1 might be functionally linked to disrupted ADMA/arginine homeostasis and impaired NO synthesis in severe malaria." (PMID 26407009, 2015). "To test the hypothesis that DDAH1 is inactivated during Plasmodium infection, we examined DDAH1 in a mouse model of severe malaria." (PMID 26407009, 2015). "Although these findings in the mouse model cannot be directly extrapolated to human malaria, it raises the possibility that the elevated ADMA/arginine ratio observed in children with severe malaria could be due in part to inactivation of DDAH1." (PMID 26407009, 2015). "In severe malaria, renal insufficiency, in addition to the hepatic DDAH1 dysfunction we present here, could contribute to dysregulation of ADMA/arginine homeostasis." (PMID 26407009, 2015). "Loss of hepatic DDAH1 activity and disruption of ADMA/arginine homeostasis may contribute to severe malaria pathogenesis by inhibiting NO synthesis." (PMID 26407009, 2015). "To determine whether severe malaria affects hepatic DDAH1 function, we assessed hepatic Ddah1 gene expression and protein levels in liver tissue from C57BL/6 mice 6 days after inoculation with P. berghei ANKA." (PMID 26407009, 2015). "DDAH1 metabolizes ADMA, so we examined changes in DDAH1 activity in mice infected with a Plasmodium berghei ANKA, a model of severe malaria." (PMID 26407009, 2015). "In this study, we identify dysregulation of ADMA/arginine homeostasis in Gambian children with severe malaria and hypothesize that ADMA clearance is impaired by hepatic DDAH1 inactivation." (PMID 26407009, 2015).
ovarian carcinoma (2 papers, 2019 to 2023). A malignant neoplasm originating from the surface ovarian epithelium. "Although this regulation has not been assessed in cancer, miR-219-5p has been reported to have a tumor suppressive role in colon cancer and ovarian cancer, which may in part relate to regulation of DDAH1." (PMID 31993367, 2019). "PRMT5, PRMT1, DDAH1, DDAH2, NOS2, ARG1, and ARG2 were all found to be up-regulated in the stage I/II or stage III/IV ovarian cancer tissues compared to normal tissues." (PMID 37684587, 2023). "Notably, gene clusters of PRMT1/PRMT5 and DDAH1/DDAH2/ARG2 persisted, while other gene tree relationships and expression significances differed between the two comparisons: normal tissue versus stage I/II ovarian cancer and stage I/II versus stage III/IV ovarian cancer." (PMID 37684587, 2023).
pancreatic cancer (2 papers, 2020 to 2025). "By uncovering complex interactions between different omics layers and identifying connections between key molecular players such as PDIA6 and DDAH1, multiomics analysis holds great promise for advancing precision medicine and improving outcomes in pancreatic cancer patients." (PMID 40719618, 2025). "The interplay between GSTP1, DDAH1 and PDIA6 highlights the complexity of redox regulation in pancreatic cancer and suggests that targeting GSTP1 may offer a new therapeutic approach for PDAC." (PMID 40719618, 2025).
age-related macular degeneration (1 paper, 2016). Age-related loss of vision in the central portion of the retina (macula), secondary to retinal degeneration. "To investigate the role of DDAH1 and DDAH2 in angiogenesis in choroidal neovascularization (CNV), a feature of age-related macular degeneration, we measured the extent of CNV induced by laser-rupture of Bruch’s membrane in heterozygous DDAH1 and homozygous DDAH2 deficient mice." (PMID 27181226, 2016).
allergic asthma (1 paper, 2014). A asthma with a basis in a pathological type I hypersensitivity reaction. "In summary, our data suggest that decreased expression of DDAH1 and DDAH2 in lungs may contribute to allergic asthma and overexpression of DDAH1 attenuates allergen-induced airway inflammation through modulation of Th2 responses." (PMID 24465497, 2014). "Our findings suggest that decreased expression of DDAH1 and DDAH2 in the lungs may contribute to allergic asthma and overexpression of DDAH1 attenuates allergen-induced airway inflammation through modulation of Th2 responses." (PMID 24465497, 2014).
cholestatic cirrhosis (1 paper, 2021). "It was shown that asymmetric-dimethylarginine (ADMA), an eNOS inhibitor which is metabolized by DDAH-1 was significantly reduced upon treatment with OCA in an animal model of cholestatic cirrhosis, due to rescue of DDAH-1 expression via activation of FXR." (PMID 34440614, 2021).
colonic tumors (1 paper, 2020). "However, our analysis of clinical samples showed the downregulation of DDAH1 and DDAH2 in colonic tumors." (PMID 32932854, 2020).
Crohn disease (1 paper, 2020). A gastrointestinal disorder characterized by chronic inflammation involving all layers of the intestinal wall, noncaseating granulomas affecting the intestinal wall and regional lymph nodes, and transmural fibrosis. "Supporting possible DDAHs involvement in predisposing to cancer development, colonic DDAH1 expression has been upregulated in patients with Crohn’s disease, solely during the disease flare, while that of DDAH2 was also upregulated during remission." (PMID 32932854, 2020).
demyelinating disorders (1 paper, 2023). "By modifying Ddah1 activity, these findings offer a unique therapeutic strategy for demyelinating disorders." (PMID 36975497, 2023).
diabetic retinopathy (1 paper, 2012). "Furthermore, AT1-R activation in the rat retina also leads to high PRMT1 and low DDAH1 expression, which is implicated in the progression of diabetic retinopathy." (PMID 22546019, 2012).
endotoxemia (1 paper, 2016). "We could previously show that DDAH1+/− mice exhibit reduced DDAH1 protein expression and elevated circulating and tissue ADMA concentrations which was associated with attenuated hemodynamic consequences in endotoxemia." (PMID 27181226, 2016).
experimental autoimmune encephalomyelitis (1 paper, 2023). An autoimmune demyelinating disease of the central nervous system that is produced experimentally in animals by the injection of homogenized brain or spinal cord in Freund's adjuvant. "In addition, experimental autoimmune encephalomyelitis showed that increasing Ddah1 expression improved the ability to remyelinate." (PMID 36975497, 2023).
Gastric tumors (1 paper, 2021). "Gastric tumors had upregulated NOS2 and downregulated ASL, PRMT2, ORNT1, and DDAH1 expression." (PMID 34439753, 2021).
gastritis (1 paper, 2026). Inflammation of the stomach. "Programmed cell death protein 1 (PD-1)/programmed death-ligand 1 (PD-L1) axis disruption depends on dimethylarginine dimethylaminohydrolase 1 (DDAH1) activity during metastasis in patients with severe gastritis, either synergizing with NO or inhibiting PD-1/PD-L1 activation in tumor growth." (PMID 41913824, 2026).
glaucoma (1 paper, 2022). Increased pressure in the eyeball due to obstruction of the outflow of aqueous humor. "Since the ADMA levels were significantly increased in the serum as well as plasma of glaucoma patients, the CDR2-induced down-regulation of DDAH1 might indicate a lesser cellular stress response of retinal cells, particularly RGCs, in vitro." (PMID 36313990, 2022).
glioblastoma (1 paper, 2023). The most malignant astrocytic tumor (WHO grade IV). "Univariate analyses also demonstrated that SLC7A7 and ASS1 were hazardous prognostic factors for glioblastoma, while DDAH1 and NOS1 were proved as protective factors for glioblastoma." (PMID 37214463, 2023).
Hypercholesterolemia (1 paper, 2025). An increased concentration of cholesterol in the blood. "Research indicates that DDAH consists of two subunits, DDAH1 and DDAH2, which are associated with cardiovascular diseases induced by hypercholesterolemia, hypertension, abdominal obesity, and diabetes mellitus." (PMID 40149398, 2025).
Intellectual disability (1 paper, 2019). "Furthermore, what is the role of cancer genes (DDAH1 and PTPN14) shown to have variants with a protective role for intellectual disability." (PMID 30824863, 2019). "This further supports the evidence that some types of cancers and intellectual disability may be mutually exclusive, generating the hypothesis that some cancer related genes like, DDAH1 and PTPN14, may act as protective against some forms of intellectual disability." (PMID 30824863, 2019).
ischemia (1 paper, 2019). A hypoperfusion of the BLOOD through an organ or tissue caused by a PATHOLOGIC CONSTRICTION or obstruction of its BLOOD VESSELS, or an absence of BLOOD CIRCULATION. "An in vivo study on ischemia/reperfusion rat models reported that rutin stimulated the DDAH/NOS pathway by upregulating both eNOS and DDAH1 expression." (PMID 31607906, 2019).
Listeria infection (1 paper, 2021). "We show that NO production is reduced in macrophages from RNF213 KO mice, suggesting that RNF213 controls Listeria infection through regulation of DDAH1 transcription and production of NO." (PMID 34804992, 2021). "Knockdown of RNF213 also results in downregulation of DDAH1, which we discover to exert antimicrobial activity against Listeria monocytogenes infection." (PMID 34804992, 2021). "We report here an antimicrobial role of DDAH1 against Listeria infection." (PMID 34804992, 2021). "Conversely, overexpression of FLAG-tagged DDAH1 significantly lowered Listeria infection levels." (PMID 34804992, 2021). "Taken together, our findings that depletion of RNF213 leads to reduced levels of DDAH1 and to lower levels of NO production suggest a potential mechanism by which RNF213 controls Listeria infection through regulation of DDAH1 transcription." (PMID 34804992, 2021).
lung adenocarcinoma (1 paper, 2022). A carcinoma that arises from the lung and is characterized by the presence of malignant glandular epithelial cells. "H19 has been shown to regulate miR-148b-3p and promote the expression of dimethylarginine dimethylaminohydrolase 1 (DDAH1) through negative feedback in lung adenocarcinoma cells resistant to gefitinib." (PMID 36188624, 2022).
lung diseases (1 paper, 2019). "Of course, further study is needed, but our findings suggest that DDAH1 potentially could be a viable therapeutic target for preventative and/or therapeutic treatments for lung diseases of the preterm infant." (PMID 31209995, 2019).
lung squamous cell carcinoma (1 paper, 2019). "In pancreatic adenocarcinoma and thymoma DDAH1 and DDAH2 mRNA is significantly increased, whilst both DDAH1 and DDAH2 expression is decreased in lung squamous cell carcinoma." (PMID 31993367, 2019).
lymph node metastasis (1 paper, 2017). "This study demonstrates that DDAH1 is frequently downregulated in clinical GC samples and its low expression is closely associated with more lymph node metastasis, lower histological differentiation, and poorer clinical outcome." (PMID 28580735, 2017).
mental disorder (1 paper, 2022). A disease that has its basis in the disruption of mental process. "No other associations with mental disorders were identified in DDAH1 co-expressed genes in any study group." (PMID 36233204, 2022). "Despite all these limitations, the present work provides preliminary evidence that DDAH1 and DDAH2 are co-regulated with genes involved in mental disorder development and derangement." (PMID 36233204, 2022).
metabolic syndrome (1 paper, 2022). A cluster of metabolic risk factors for CARDIOVASCULAR DISEASES and TYPE 2 DIABETES MELLITUS. "Thus, these SNPs of Ddah1 were likely associated with metabolic syndrome (MS), which was regarded as an increased risk factor of low bone mineral density." (PMID 35013196, 2022). "Thus, these SNPs of Ddah1 are likely associated with metabolic syndrome including metabolic bone diseases." (PMID 35013196, 2022).
migraine (1 paper, 2015). "Since large amounts of ADMA and DDAH-1 have been detected in the brain and spinal cord, probably ADMA/DDAH-1 pathway may have a role also in neuronal, inflammatory and other non-cardiovascular pathologies, as migraine pain, where NO has pivotal role." (PMID 26272684, 2015).
multiple sclerosis (1 paper, 2016). A progressive autoimmune disorder affecting the central nervous system resulting in demyelination. "Similarly our genetic analysis for BLC revealed a significant association with SNPs located in DDAH1 (rs7541151, p = 6.44 × 10−9), a gene that has been associated with multiple sclerosis (MS)." (PMID 36647296, 2016).
Myocardial fibrosis (1 paper, 2022). "Several therapeutic targets for myocardial fibrosis, such as Ddah1, Meox1, and Ctrhc1, have been identified by single cell sequencing analysis and have provided novel theoretical targets for the treatment of myocardial fibrosis." (PMID 35799890, 2022).
non-alcoholic fatty liver disease (1 paper, 2025). "Moreover, in vivo studies have demonstrated that overexpression of DDAH1 mitigates metabolic dysfunctions, such as lipid accumulation and inflammation, in high-fat-fed mice and mice with non-alcoholic fatty liver disease (NAFLD)." (PMID 40149398, 2025).
osteoarthritis (1 paper, 2023). A noninflammatory degenerative joint disease occurring chiefly in older persons, characterized by degeneration of the articular cartilage, hypertrophy of bone at the margins and changes in the synovial membrane. "One group found that ADMA promoted SOX9 destabilization, which was mediated by DDAH1 in osteoarthritis." (PMID 37359559, 2023). "DDAH1 expression was decreased, while DDAH1 was increased in osteoarthritis patients." (PMID 37359559, 2023). "Because DDAH1 was an ADMA hydrolase, mice with global or chondrocyte-conditional knockdown of DDAH1 displayed a rapid development of osteoarthritis." (PMID 37359559, 2023). "Hence, upregulation of DDAH1 to inhibit ADMA levels and regulate USP7-mediated SOX9 deubiquitination could be a useful strategy for the treatment of osteoarthritis." (PMID 37359559, 2023).
osteoporosis (1 paper, 2022). A condition of reduced bone mass, with decreased cortical thickness and a decrease in the number and size of the trabeculae of cancellous bone (but normal chemical composition), resulting in increased fracture incidence. "Therefore, our initial aim was to investigate if the loss-of-function Ddah1 promoter polymorphism is associated with osteoporosis." (PMID 35013196, 2022). "Although the underlying mechanism may be complicated, our study at least demonstrated that ADMA and DDAH1 levels are associated with disuse-related osteoporosis, while deletion of Ddah1, a mechanical response gene, is contributed to the reduction of bone formation." (PMID 35013196, 2022). "Our findings also inform that further studies can be focused on potential therapeutic approaches related to reducing ADMA or enhancing DDAH1 for preventing osteoporosis." (PMID 35013196, 2022).
parasitic infections (1 paper, 2014). "In our experiment, the OAT but also the N(G),N(G)-dimethylarginine dimethylaminohydrolase 1 (DDAH1, a NOS inducer) proteins were less abundant during the infection suggesting that the NOS regulation is altered by the infection as it has been observed in several parasitic infections." (PMID 24967735, 2014).
rectal adenocarcinomas (1 paper, 2020). "While consistent with ADMA accumulation, our observation contradicts the results of RNA-seq expression data analysis, indicating higher DDAH1 expression level in tumors than normal tissue in colonic and rectal adenocarcinomas." (PMID 32932854, 2020).
retinal ischemia (1 paper, 2016). A ischemic disease that involves the retina. "Future studies using viable DDAH1−/− or cell-specific conditional knockout mice are warranted to determine the role of DDAH1 in retinal ischemia and neovascularization with greater confidence." (PMID 27181226, 2016). "To determine the effect of reduced DDAH1 and absent DDAH2 activity on retinal ischemia and neovascularization we investigated DDAH1+/− and DDAH2−/− deficient mice in two established models of ocular neovascularization." (PMID 27181226, 2016). "Finally, DDAH1+/− and DDAH2−/− deficient mice were studied in the oxygen-induced retinopathy (OIR) model, a model used to emulate retinal ischemia and neovascularization, and VEGF and ADMA levels were quantified by ELISA and liquid chromatography tandem mass spectrometry." (PMID 27181226, 2016). "To do this we investigated the expression of ADMA and L-NMMA in the ischemic murine retina and characterized DDAH1 and DDAH2 knockout mice in health and in an established model for retinal ischemia and neovascularization." (PMID 27181226, 2016). "The aim of this study was to determine the roles of DDAH1, DDAH2, ADMA and L-NMMA in retinal ischemia-induced angiogenesis." (PMID 27181226, 2016).